SLC2A1 (solute carrier family 2 member 1)
Diseases named in the same sentence as SLC2A1 in open-access papers (continued):
Sharing a sentence is not in itself a finding about the gene and the disease.
cancer (continued). "Therefore, the reliability of a PET scan with 18FDG as the probe in cancer detection still depends solely on SLC2A1 (and SLC2A3)." (PMID 38339256, 2024). "Furthermore, SLC2A1 has shown prognostic significance and plays a role as an immune marker in various other cancers." (PMID 38517368, 2024). "Many TME-related genes (such as VEGFA, MMP14, CCND1, MAP2K1, SLC2A1) and actin cytoskeleton-associated genes (such as ITGB4, ITGA6, ACTG1, VCL) were downregulated, suggesting a less favorable TME and an altered cytoskeleton network in ISO-treated cancer cells." (PMID 38339062, 2024). "SLC2A1, the glucose transporter, could encourage the growth, invasion, resistance to chemotherapy, and metastasis of cancer cells by controlling aerobic glycolysis." (PMID 38345559, 2024). "As HNSCCs are among cancers with highest expression of GLUT1/SLC2A1, BAY-876 may have enhanced efficacy in HNSCC." (PMID 39060287, 2024). "Previous studies have reported SLC2A1 as a prognostic marker in various cancers, including NSCLC." (PMID 39858431, 2024). "Importantly, SLC2A1 has been reported to promote cancer development by regulating cell proliferation." (PMID 38517922, 2024). "Furthermore, the expression of glucose transporter solute carrier family 2 member 1 (Slc2a1) has been shown to be increased in cancer; it is thought to regulate glycolysis and proliferation in cancer cells." (PMID 37367058, 2023). "Additionally, SLC2A1 is a major facilitator glucose transporter overexpressed in numerous cancers, including EAC, and with roles not only in glycolysis but also epithelial–mesenchymal transition, hypoxia, cell-cycle regulation and DNA repair." (PMID 38139823, 2023). "For instance, HIF1α is a direct target of miR-143-5p, which inhibits tumorigenesis, cancer proliferation, and progression by suppressing HIF1α expression at the post-transcriptional level and solute carrier family 2 member 1 (GLUT1) pathway downstream of HIF1α signaling." (PMID 37583933, 2023). "The glucose transporter SLC2A1 and other members of the protein family were strongly downregulated in the Tks4 KO cells, implying that Tks4 is important for the signaling pathways that maintain cancer progression." (PMID 36674824, 2023). "Their analysis indicated that a high level of SLC2A1 correlated with poor prognosis across cancers." (PMID 37833332, 2023). "Most of these functions of SLC2A1 have been studied in various types of cancers." (PMID 36358765, 2022). "Collectively, SLC2A1 may provide new strategies for pan-cancer treatment, especially cancer immunotherapy." (PMID 36358765, 2022). "The previous results confirmed that SLC2A1 is highly expressed in most cancers at the mRNA level, but whether SLC2A1 is also highly expressed at the protein level needed further exploration." (PMID 36358765, 2022). "To further explore the role of SLC2A1 as a prognostic biomarker in cancer, we analyzed TCGA Pan-Cancer survival data, including OS, DFS, disease-specific survival (DSS), and progression-free survival (PFS), and presented the results in the form of a forest diagram." (PMID 36712872, 2022). "First, the analysis of SLC2A1 expression in cancer was performed." (PMID 36712872, 2022). "Therefore, we have no specific and complete cases with data to identify the benefit of anti-SLC2A1-targeting drugs in the survival of cancer." (PMID 36358765, 2022). "In addition, phosphorylation and ubiquitination of SLC2A1 were altered in a variety of cancers, predominantly in gastric, bladder, and head and neck tumors." (PMID 36712872, 2022). "Additionally, SLC2A1 also has prognostic significance or an immune marker role in many other cancers." (PMID 36712872, 2022). "GEPIA2.0 was used to identify the prognostic significance of SLC2A1 expression in pan-cancer." (PMID 36712872, 2022). "This indicated that the mechanism of m6A methylation may play a vital role in the regulation of SLC2A1 expression in cancer tissues." (PMID 36358765, 2022).
cancer (continued). "In summary, SLC2A1 may be overexpressed in cancers tissues by hypoxia and promote cancer-cell proliferation and metastasis by regulating cancer glycometabolism, the cell-cycle checkpoint, DNA repair process, and EMT." (PMID 36358765, 2022). "We observed high expression levels of SLC2A1 with poor prognosis in most cancers." (PMID 36358765, 2022). "In addition, we analyzed the protein expression of SLC2A1 of 2002 patients across 14 cancer subtypes in the CPTAC samples based on UALCAN data." (PMID 36358765, 2022). "Additionally, the expression of SLC2A1 is significantly upregulated in higher pathologic stages in various cancers." (PMID 36358765, 2022). "The results confirmed that down-regulation of SLC2A1 could effectively block the periodic transformation of H1299 and A549 and promote the apoptosis of cancer cells." (PMID 35517408, 2022). "SLC2A1 plays a crucial role in the process of cell glycometabolism, whether in cancer or normal cells." (PMID 36358765, 2022). "The results showed that SLC2A1 is a hazard factor for the OS of patients in most cancers." (PMID 36358765, 2022). "SLC2A1 may play a crucial role in cancer cell proliferation and metastasis through multiple mechanisms, such as regulating the cell-cycle checkpoint, DNA repair process, EMT, CAFs and neutrophils in the TME, and T-cell exhaustion." (PMID 36358765, 2022). "We explored the potential mechanism of SLC2A1 in pan-cancer through bioinformatics analysis." (PMID 36358765, 2022). "The mechanism of SLC2A1 in pan-cancer has rarely been explored." (PMID 36358765, 2022). "We used 24 types of cancers in the UALCAN database to analyze the methylation of SLC2A1." (PMID 36358765, 2022). "SLC2A1 has been proposed as a putative driver gene in various cancers." (PMID 36358765, 2022). "We further analyzed SLC2A1 mRNA expression level in different human cancers utilizing TCGA cohort." (PMID 35399515, 2022). "We found hypomethylation in the SLC2A1 promoter region in various cancer tissues, which might, to some extent, explain the SLC2A1 mRNA overexpression in the corresponding cancers." (PMID 36358765, 2022). "Whether the high expression of SLC2A1 in cancers affects the prognosis of patients is an issue of concern to researchers." (PMID 36358765, 2022). "Studies have shown that high SLC2A1 expression is suggestive of poor prognosis in most cancers." (PMID 36712872, 2022). "SLC2A1 promoter DNA methylation levels were abnormal in 10 cancers." (PMID 36712872, 2022). "This suggests that the translational and post-translational modification processes of SLC2A1 may be abnormal in these cancers." (PMID 36712872, 2022). "SLC2A1 might serve as an attractive pan-cancer biomarker for providing new insights into cancer therapeutics." (PMID 36358765, 2022). "This is the first study in which the role of SLC2A1 at the pan-cancer level was explored." (PMID 36358765, 2022). "Among the many members, solute carrier family 2 member 1 (SLC2A1) encodes a glucose transporter, GLUT1, that is critical in the metabolism of glucose, which is an energy source for cell growth that contributes to cancer progression and development." (PMID 33735188, 2021). "One hypothesis is that SLC2A1 increases glucose metabolism and provides a high energy source for cancer cells." (PMID 33735188, 2021). "Meanwhile, SLC2A1 was reported to play a role as a drug target for cancer therapy." (PMID 34906142, 2021). "ATRA most effectively reduced the growth of cancer cell lines with high SLC2A1 expression [ATRA: r = -0.727, p = 0.041 (Pearson’s correlation) and 0.028 (Student’s t-test); fluorouracil: r = -0.427, p = 0.292 and 0.154; oxaliplatin: r = 0.353, p = 0.437 and 0.562]." (PMID 33735188, 2021).
cancer (continued). "In this study, PEG–BA downregulated SLC2A1 and may decrease cellular glucose uptake effectively, depriving cancer cells of much-needed energy to grow and proliferate." (PMID 34063891, 2021). "The expression level of SLC2A1 is frequently upregulated in multiple cancers, including LUAD." (PMID 34906142, 2021). "Within the favorable genes, UNC13B, and SFXN2 cover nine cancer types and in the same way, SLC2A1, PLS3, SLC16A1, and SLC16A3 within the unfavorable set of genes and could serve as novel target structures." (PMID 32599841, 2020). "The 'Warburg' phenotype of cancer cells, characterized by enhanced glycolysis, is mediated mainly by an aberrant expression of glucose transporter type 1 (GLUT1), also known as solute carrier family 2, facilitated glucose transporter member 1 (SLC2A1), a member of the glucose transporter family." (PMID 32777161, 2020). "In addition, the interactions among GRB2, EGFR, HIF1A, and SLC2A1 were also highly correlated with cancer in the KEGG “Pathways in cancer” (pathway #5200)." (PMID 32170141, 2020). "Indeed, certain cancer cells upregulate the gene expression of the glucose transporters GLUT1 (SLC2A1) and GLUT3 (SLC2A3) to increase glucose uptake, which correlates with poor prognosis." (PMID 31288376, 2019). "Moreover, other studies have shown that a high SLC2A1 expression level is a marker of poor prognosis for several types of cancer." (PMID 29855388, 2018). "The avidity of cancer cells for glucose, mainly mediated by the upregulation of glucose transporter 1 (GLUT1; also known as SLC2A1), contributed to the development of fluorodeoxyglucose-positron emission tomography (FDG-PET) techniques for cancer detection and monitoring." (PMID 29991569, 2018). "Glucose transporter 1 (GLUT1), the uniporter protein encoded by the SLC2A1 gene, is a key rate-limiting factor in the transport of glucose in cancer cells, and frequently expressed in a significant proportion of human cancers." (PMID 28187435, 2017). "18FDG-PET imaging is useful when cancers express high levels of SLC2A1 or SLC2A3." (PMID 28978124, 2017). "We find stromal HIF-1α expression to be highly significantly associate with SLC2A1 mRNA expression where the corresponding protein, GLUT1, is known as an important protein facilitating increased glycolysis on which the cancer cells and hypoxic cells are dependent." (PMID 27634881, 2016). "Thus, those cancer cells with extremely high levels of SLC2A1, such as those hypermethylated at DERL3, will be very sensitive to drugs that downregulate SLC2A1 expression, such as direct (shikonin) or indirect (AKT inhibitor VIII) PKM2 inhibitors." (PMID 24699711, 2014). "Moreover, cancer cells preferentially located in cluster 2 may affect the uptake of other albumins because various receptors (e.g., Slc2a1, glucose transporter 1 gene) are expressed on the cell membrane to actively collect ligands." (PMID 41355949, 2026). "Thus, SLC2A1 may influence UCEC progression by modulating cancer cell metabolism, and there may be a connection between MPST and UCEC development due to its role in cysteine and methionine metabolism." (PMID 40746529, 2025). "We found that the overall mutation rate of SLC2A1 in pan-cancer is only 1.8%, which could not explain the high transcriptome expression of SLC2A1 in most cancers." (PMID 36358765, 2022). "Thus, we analyzed he genetic alteration status of SLC2A1 in the TCGA pan-cancer cohorts." (PMID 36358765, 2022). "These analyses point out that SLC2A1 may be a possible target for cancer targeted therapy." (PMID 35399515, 2022). "Furthermore, we found a strong positive correlation between SLC2A1 and hypoxia in most cancers." (PMID 36712872, 2022). "Therefore, our results suggested that SLC2A1 may play an important role in the growth and metabolism of cancers, and they support the possibility of SLC2A1 being used as a biomarker for the diagnosis of pan-cancer." (PMID 36358765, 2022).
cancer (continued). "However, research on SLC2A1 is still confined to a few cancer species." (PMID 36712872, 2022). "This suggests that SLC2A1 may affect immune cells, as well as cancer growth suppression." (PMID 33735188, 2021). "HIF-1 induces the expression of solute carrier family 2 member 1 (SLC2A1) and solute carrier family 2 member 3 (SLC2A3), which encode GLUT1 and GLUT3 respectively, to promote glucose uptake to meet the insatiable demand of glucose for growth of hypoxic cancer cells." (PMID 34359884, 2021). "Thus, we speculate ACLY and SLC2A1 may serve as critical linker of metabolic and histone acetylation in these cancer types." (PMID 31828117, 2019). "Thus, further characterization of the contribution of SLC2A6 to glucose uptake relative to SLC2A1/3 may illuminate our understanding of cancer cell metabolism." (PMID 31723131, 2019). "Thus, they suggested a putative role for SLC2A1 in invasiveness of cancer cells." (PMID 27540529, 2016). "Thus, we wondered whether SLC2A1 expression levels mediated by DERL3 degradation affected cancer cell glucose-dependent growth and lactate production." (PMID 24699711, 2014). "A similar analysis was performed at the mRNA level, revealing BACH2 (9 tissue-specific interactions in COAD) and SLC2A1 and TBL1XR1 (7 interactions in different cancer tissues) as the most recurrent mRNAs." (PMID 41183125, 2025). "To investigate the impact of SLC2A1 on cancer patient survival, we analyzed its correlation with OS, DSS, DFI, and PFI across cancer types." (PMID 40276602, 2025). "In lung cancer, SLC2A1 has been found to interact with KRAS, another key cancer gene, enhancing the Warburg effect and tumorigenesis." (PMID 40746529, 2025). "miR‐5586‐5p also suppresses the expression of glycolytic genes, lactate dehydrogenase A (LDHA), hexokinase 2 (HK2), phosphoglycerate kinase 1 (PGK1), and solute carrier family 2 member 1 (SLC2A1), thereby suppressing glycolysis and cancer progression." (PMID 40448344, 2025). "We analyzed the expression levels of the SLC2A1 and MPST genes using cancer datasets from the TCGA database." (PMID 40746529, 2025). "In summary, this study investigated the expression of SLC2A1 and MPST across different cancer types." (PMID 40746529, 2025). "The correlation between SLC2A1 expression and eight immune checkpoints (CTLA4, PDCD1, TIGIT, LAG3, CD274, HAVCR2, PDCD1LG2, and SIGLEC15) was further investigated across multiple cancer types." (PMID 40824962, 2025). "The first glucose transporter that was found to be upregulated in the plasma membrane of cancer cells was GLUT1, also identified as SLC2A1." (PMID 38339256, 2024). "In contrast to SLC2A1 and SLC2A3, SLC5A2 is a concentrative transporter and thus has a greater efficiency than SLC2A1/SLC2A3 in transporting glucose into cancer cells." (PMID 38339256, 2024). "The protein expression levels of PLK1, SLC2A1, ANGPTL4, and CDKN3 in LUAD tissues were all significantly higher than those in para-cancer tissues." (PMID 38345559, 2024). "Preclinical data suggest that solute carrier family two facilitated glucose transporter member 1 (SLC2A1) and lactate dehydrogenase A (LDHA) are viable drug targets for cancer treatment." (PMID 38555429, 2024). "These genes are GAPDH, FSCN1, SLC2A1, FAM83A, PLEK2, and GJB3, some of which have been previously documented in various cancer types." (PMID 38370379, 2024). "Central carbon metabolism in cancer-related genes, i.e., SLC16A3, FGFR3, LDHA, PGAM1, and SLC2A1, significantly reduced after treatment with CTPPPPD." (PMID 39275122, 2024). "The glucose transporter SLC2A1 (GLUT1) is a key target of MYC and allows increased glucose uptake via cancer cells by enhancing its activity." (PMID 37443779, 2023). "Solute carrier family 2 member 1 (SLC2A1), known as glucose transporter 1 (GLUT1), is reported to express highly in many cancers and promote cancer growth." (PMID 37604837, 2023).
cancer (continued). "Solute carrier family 2 member 1 (SLC2A1), also known as glucose transporter 1 (GLUT1), is an energy source for cell growth that lends favor to cancer development and progression." (PMID 35938001, 2022). "In some cancers, such as LIHC and THYM, we found that SLC2A1 expression was positively correlated with immune checkpoint genes, while being negatively correlated in HNSC, LUSC, and TGCT." (PMID 36712872, 2022). "The univariate Cox regression analysis showed that SLC2A1 expression levels were strongly related to OS in 10 cancers, DFS in four cancers, DSS in eight cancers, and PFS in eight cancers." (PMID 36712872, 2022). "Our PPI network analysis identified four hub genes (SLC2A1, VEGFA, JUN, and PTGS2) enriched in the cancer-related pathways." (PMID 36482897, 2022). "We performed a correlation analysis between SLC2A1 and TMB and MSI, and we found that SLC2A1 expression is significantly correlated with TMB in 13 cancer types and with MSI in 10 cancer types." (PMID 36358765, 2022). "The results also showed that SLC2A1 is a hazard factor for the PFI, DFI and DSS of patients in various cancers." (PMID 36358765, 2022). "UCSCXenaShiny based on the cancer genomic atlas pan-cancer data and GEPIA2.0 database were used to assess the prognostic significance of SLC2A1 in pan-cancer." (PMID 36712872, 2022). "Thus, we suggest that SLC2A1 could play an important role in promoting cancer progression." (PMID 33735188, 2021). "SLC2A1 (or glucose transporter 1, GLUT1), which transports glucose into cells, is required in glucose metabolism for fulfilling the high energy demands of cancer cells." (PMID 33664854, 2021). "Elevated expression of several key glycolytic enzymes, including SLC2A1/GLUT1, HK2, ENO1, PGK1, PDK1, PDK4, and PFKFB3, was found to correlate with resistance in some cancer cell lines and clinical tissue samples." (PMID 34645978, 2021). "Previous literature has indicated that β-catenin-mediated c-Myc expression upregulates several glycolytic genes, including SLC2A1 (GLUT1) and LDHA, thereby promoting the Warburg effect in cancer cells." (PMID 34575112, 2021). "By performing qRT-PCR, we observed that cancer cells exposed to SPP1 exhibited a significantly increased gene expression in EMT-related molecule CD44 and glycolytic genes including SLC2A1 and ENO2 at 48 h." (PMID 34676217, 2021). "Glucose transporters, in particular SLC2A1 (GLUT1), are a key rate-limiting factor in glucose metabolism in cancer cells." (PMID 33324631, 2020). "We found that the mRNA levels of both SLC2A1 and SLC2A3 were significantly upregulated in cancer tissues of these CRC patients." (PMID 32873793, 2020). "Our research clarifies some key metabolic genes, ACLY, SLC2A1, KAT2A, and DNMT3B, which are most disordered and indirectly contribute to the dysfunction of histone acetylation and DNA methylation in cancer." (PMID 31828117, 2019). "Further study is needed to investigate ACLY, SLC2A1, and KAT2A in the histone acetylation function across cancer types." (PMID 31828117, 2019). "ACLY, SLC2A1, KAT2A, and DNMT3B are the critical genes contributing to epigenetic dysfunction across cancers." (PMID 31828117, 2019). "Pair-wise tests presented significant (p < 0.05) hypo-methylated genes between Cancer/control and Family/control pairs on SEPT9 at the intron region, SLC2A1/GLUT1 at the promoter region, and SLC2A3/GLUT3 at the intron region." (PMID 29876008, 2018). "In conclusion, to the best of our knowledge, our study is the first to demonstrate that miR-328 is potentially able to inhibit SLC2A1 and consequently regulate GLUT1-mediated glycolytic activity in cancer cells." (PMID 29374351, 2018). "GLUT1, or solute carrier 2A 1 (SLC2A1), has been shown to play a role in cancer cell metabolic reprogramming." (PMID 26023239, 2015). "Both SLC2A1 and MPST have been identified as important regulators in cancer." (PMID 40746529, 2025).